SCG3 (secretogranin III)
Diseases named in the same sentence as SCG3 in open-access papers:
SCG3 is named in the same sentence as 43 diseases in open-access papers, as found by Europe PMC text mining. Sharing a sentence is not in itself a finding about the gene and the disease. The quoted sentences say what the papers report.
Obesity (6 papers, 2013 to 2025). Accumulation of substantial excess body fat. "Another example is SCG3, an obesity-associated gene for which inter-species DE is restricted to a few cell types, including acinar (pancreatic) cells." (PMID 37697401, 2023). "GWAS have pinpointed SNPs in the SCG3 gene associated with obesity." (PMID 40405979, 2025). "Furthermore, cohort studies suggest that diminished SCG3 levels are linked to an elevated risk of obesity." (PMID 40405979, 2025). "SCG3 has also been associated with obesity in humans and puberty in cattle." (PMID 39272257, 2024). "Interestingly, several loci on chromosomes were linked with MetS, diabetes, and obesity, including regions on chromosome 15q.The gene encoding SCG3, which is located on chromosome 15q as well, was therefore associated with obesity." (PMID 31514320, 2019). "In other words, decreased SCG3 levels may be associated with a higher risk of obesity." (PMID 31514320, 2019). "Utilizing the BLISS method, we successfully identified 89 proteins implicated in the comorbid risk of obesity and depression across the deCODE, UKBPP, and ARIC databases, with SCG3 and FLRT2 detected in all three." (PMID 40405979, 2025).
glioma (5 papers, 2021 to 2024). A benign or malignant brain and spinal cord tumor that arises from glial cells (astrocytes, oligodendrocytes, ependymal cells). "Thus, IHC-based SCG3 protein detection can be integrated into other diagnostic modalities for more precise diagnosis in glioma patients." (PMID 34257545, 2021). "Many of them, such as CDHR1, DLL1, DLL3 and SCG3, have been reported to be potential therapeutic targets for glioma treatment." (PMID 35456975, 2022). "Together, our result demonstrated a wide and varying staining of SCG3 in gliomas, as well as an intensive staining in neurons of normal brain tissues." (PMID 34257545, 2021). "In this study, we uncovered the value of SCG3 as a protein marker for glioma diagnosis and prognostication." (PMID 34257545, 2021). "In glioma, SCG3 has been recognized as a signature gene for the proneural subtype of GBMs, and as a predictor for favorable prognosis in GBM patients." (PMID 34257545, 2021). "In this study, the IHC method was used to detect SCG3 protein expression on a glioma tissue microarray (TMA)." (PMID 34257545, 2021). "The TMA was made up of 267 cases of primary glioma specimens, among which 226 cases got successful SCG3 quantification." (PMID 34257545, 2021). "Both the TCGA analysis and microarray study showed that IDH-mutant/1p19q-codeleted gliomas had the highest level of SCG3 expression among the three subtypes of grade II/III gliomas." (PMID 34257545, 2021). "Our results show that SCG3 is a potential protein marker, that will facilitate glioma precise diagnosis." (PMID 34257545, 2021). "We also observed that SCG3 expression varied significantly among different types of gliomas, especially it inversely correlated with glioma malignancy grades." (PMID 34257545, 2021). "SCG3 protein expression correlates inversely with glioma malignancy and predicts favorable clinical outcomes in GBM patients." (PMID 34257545, 2021). "Taken together, SCG3 expression was significantly higher in IDH-mutant/1p19q-codeleted gliomas than the other subtypes of glioma, and SCG3 transcriptional activity was decreased in the mesenchymal subtype of GBMs." (PMID 34257545, 2021). "SCG3 protein was detected in more than a half (57.5%) of gliomas by the IHC method, indicating high prevalence of SCG3 protein expression in gliomas." (PMID 34257545, 2021). "The results from Western blotting and quantitative real-time PCR (qPCR) also verified the inverse correlation of SCG3 with glioma malignancy grades." (PMID 34257545, 2021). "Given that SCG3 functions in mature neurons and it down-regulates when glioma cells are in a dedifferentiated state, this finding implicates SCG3 protein expression as an indicator of differentiated state for glioma diagnosis." (PMID 34257545, 2021). "Herein, we examined SCG3 protein expression in different types of gliomas, and investigated the correlation of its expression with clinicopathologic characteristics as well as genetic features in gliomas." (PMID 34257545, 2021). "Moreover, we defined the case having any discernible SCG3 staining as a SCG3-positive case and compared the proportions of SCG3-positive cases in each type of gliomas." (PMID 34257545, 2021). "This is the first study reporting SCG3 protein expression in gliomas." (PMID 34257545, 2021). "Therefore, SCG3 expression was inversely correlated with glioma malignancy and trended to be the highest level in oligodendroglial tumors." (PMID 34257545, 2021). "A total of 57.5% (130/226) glioma cases had any discernible SCG3 staining." (PMID 34257545, 2021). "Additionally, concerning to the extremely high prevalence of SCG3 expression in ODs, whether SCG3 engaging pathogenesis of this type of glioma requires further mechanism studies in the future." (PMID 34257545, 2021). "Consistently, the proportion of SCG3-positive cases was 100% in IDH-mutant and 1p19q-codeleted gliomas, higher than 80 or 58.3% in the other two subtypes." (PMID 34257545, 2021).
glioma (continued). "In addition, 5 hub genes in hub network 2 were related to the poor prognosis of gliomas, including F5, IGFBP5, TNC, SCG3, and IGFBP3." (PMID 35387222, 2022). "Together, our result demonstrates that presence of SCG3 protein expression independently predicted favorable prognosis in GBM patients, indicating the potential of SCG3 as a protein prognostic biomarker of gliomas." (PMID 34257545, 2021). "The staining pattern of SCG3 was cytoplasmic in glioma cells; no vascular structural enhancement was noted throughout the tumor tissue." (PMID 34257545, 2021). "To investigate the correlations of SCG3 protein expression with the clinicopathological and genetic features in glioma, we semi-quantified SCG3 expression levels by the SCG3 staining extent in each spot of TMA and compared them between different types of gliomas." (PMID 34257545, 2021). "We did not observe significant difference of SCG3 expression between gliomas grouped by other common genetic features in gliomas, such as TERT promoter mutations and MGMT promoter methylation." (PMID 34257545, 2021). "However, neither the TCGA analysis nor microarray study showed a correlation of SCG3 expression with prognosis for grade II/III glioma patients." (PMID 34257545, 2021). "However, there is no report on SCG3 protein expression in gliomas." (PMID 34257545, 2021). "EGFR, BCAN, SOX2, PTN and CCN3 were found to be highly elevated in the glioma tumorous tissue with prominent fold change value, while other DE-ARGs, such as CLU, SCG3, showed no distinct expression alteration." (PMID 39033204, 2024).
diabetic retinopathy (4 papers, 2019 to 2024). "Secretogranin III (Scg3) is a diabetic retinopathy (DR)-restricted angiogenic factor identified in preclinical studies as a target for DR therapy." (PMID 39273454, 2024). "Secretogranin III (SCG3) has been shown to be involved in anti-angiogenesis in diabetic retinopathy." (PMID 30626092, 2019). "Additionally, employing the revolutionary technology of comparative ligandomics, Scg3 was recently demonstrated to be a novel angiogenesis growth factor in a mouse model of diabetic retinopathy." (PMID 36443679, 2022). "Li’s study found that Secretogranin III (Scg3) and VEGF exerted similar effects, and both could affect the growth of neovascularization in diabetic retinopathy." (PMID 36443679, 2022).
asthma (3 papers, 2015 to 2024). "The 15q21 has already been described in GWA of asthma, with the most associated genes being RORA, SMAD3 and SCG3." (PMID 26635092, 2015).
diabetes (3 papers, 2019 to 2023). "Using a newly developed technology called ligandomics, we recently discovered secretogranin III (Scg3) as a diabetes-selective angiogenic and vascular leakage factor that preferentially binds to diabetic over healthy retinal vasculatures." (PMID 37445707, 2023). "The findings suggest that Scg3, in contrast to VEGF, is a highly diabetes-restricted retinal vascular leakage factor." (PMID 37445707, 2023).
retinopathy of prematurity (3 papers, 2023 to 2024). A bilateral retinopathy characterized by neovascularization, scarring, retinal detachment, and eventually blindness. "Anti-Scg3 humanized antibodies (hAbs) also inhibit pathological but not physiological angiogenesis in animal models of retinopathy of prematurity (ROP)." (PMID 37445707, 2023). "We previously reported the advantage of anti-Scg3 ML49.3 mAb and EBP2 hAb, which stringently inhibits pathological but not physiological angiogenesis in animal models of retinopathy of prematurity (ROP)." (PMID 39273454, 2024). "Scg3-neutralizing Abs alleviated CNV, DR and retinopathy of prematurity (ROP) in mouse models with an efficacy equivalent to that of aflibercept." (PMID 37509549, 2023).
glioblastoma (2 papers, 2019 to 2021). The most malignant astrocytic tumor (WHO grade IV). "The lowest SCG3 expression was observed in glioblastomas (GBMs), especially in the mesenchymal subtype." (PMID 34257545, 2021).
metabolic syndrome (2 papers, 2013 to 2019). A cluster of metabolic risk factors for CARDIOVASCULAR DISEASES and TYPE 2 DIABETES MELLITUS. "SNP rs3764220 (A-allele), which is found in the promoter region of the SCG3 gene, is associated with metabolic syndrome-related physiological changes, including dyslipidemia, hypertension, and impaired glucose tolerance, with increased risk of cardiovascular disease-related morbidity and mortality." (PMID 23964269, 2013).
Parkinson disease (2 papers, 2016 to 2021). A progressive degenerative disorder of the central nervous system characterized by loss of dopamine producing neurons in the substantia nigra and the presence of Lewy bodies in the substantia nigra and locus coeruleus. "It has also been reported in the context of Parkinson’s disease, in an in vitro model, where SH-SY5Y cell exposure to the neurotoxin paraquat resulted in decreased SCG3 expression levels." (PMID 27186164, 2016).
Alzheimer disease (1 paper, 2016). A progressive, neurodegenerative disease characterized by loss of function and death of nerve cells in several areas of the brain leading to loss of cognitive function such as memory and language. "SCG3, part of the granin family involved in the secretory granule biogenesis and neurotransmitter storage and transport, can be accumulated in the senile plaques of Alzheimer’s disease patients." (PMID 27186164, 2016).
central obesity (1 paper, 2019). "Specifically, elevated SCG3 levels were found in subjects with high fasting plasma glucose (FPG) levels, central obesity, or hypertriglyceridemia." (PMID 31514320, 2019).
Cognitive impairment (1 paper, 2024). Abnormal cognition is characterized by deficits in thinking, reasoning, or remembering. "Additional markers of alterations in nerve tissue repair (SPON-1 and NFASC) were elevated in those with cognitive impairment and SCG3, suggestive of brain–gut axis disturbance, was elevated in gastrointestinal symptoms." (PMID 38589621, 2024).
corneal neovascularization (1 paper, 2022). New blood vessels originating from the corneal veins and extending from the limbus into the adjacent corneal stroma. "The present study assessed the effect of anti-Scg3 on human umbilical vein endothelial cells (HUVECs) and an animal model of corneal neovascularization (CNV) in vivo." (PMID 36443679, 2022).
coronary heart disease (1 paper, 2022). "In contrast, UNC5D, ST3GAL6, SCG3, and IGFBP1, which are negatively affected by noisy workplace environments, are potentially protective factors against coronary heart disease (UNC5D), type 2 diabetes (UNC5D), tinnitus (ST3GAL6, SCG3), and rheumatoid arthritis (IGFBP1)." (PMID 35602164, 2022).
depression (1 paper, 2025). "Although direct evidence connecting SCG3 to depression is absent, our findings propose a potential role for SCG3 in the pathophysiology of depression." (PMID 40405979, 2025).
hepatocellular carcinoma (1 paper, 2021). A malignant tumor that arises from hepatocytes. "SCG3 promotes proliferation of hepatocellular carcinoma cells and its transcript in peripheral blood predicts worse prognosis for REST-deficient small cell lung cancer." (PMID 34257545, 2021). "SCG3 participates in pathogenesis of hepatocellular carcinoma and is widely expressed in various neuroendocrine tumors." (PMID 34257545, 2021).
Hyperglycemia (1 paper, 2019). An increased concentration of glucose in the blood. "Additionally, proinsulin was found to be insufficiently converted into the mature form, insulin, in islet cells, thus leading to hyperglycemia, in SCG3-knockout mice fed a high-fat/high-sucrose diet." (PMID 31514320, 2019). "Therefore, our results indicate that there was a compensatory increase in SCG3 formation which enhanced insulin secretion to overcome the hyperglycemia produced by IR." (PMID 31514320, 2019).
hypertriglyceridemia (1 paper, 2019). A laboratory test result indicating elevated triglyceride concentration in the blood. "Specifically, there were higher serum SCG3 levels in subjects with high FPG levels, larger WCs, or hypertriglyceridemia." (PMID 31514320, 2019).
malignant glioma (1 paper, 2021). A grade III or grade IV glioma arising from the central nervous system. "In this study, we uncovered IDH-mutant/1p19q-codeleted ODs not only exhibited 100% prevalence of SCG3 protein expression, but also expressed the highest levels among all types of malignant gliomas." (PMID 34257545, 2021).
multiple sclerosis (1 paper, 2016). A progressive autoimmune disorder affecting the central nervous system resulting in demyelination. "SCG3 and SCG2 were previously evaluated as potential biomarkers of multiple sclerosis and decreased levels were observed for SCG3 and SCG2 in serum and CSF samples of multiple sclerosis patients." (PMID 27186164, 2016).
neuroendocrine tumors (1 paper, 2021). "SCG3 is also expressed widely in several tumors including some neuroendocrine tumors and prostate cancer." (PMID 34257545, 2021).
oligodendroglioma (1 paper, 2021). A well-differentiated (WHO grade II), diffusely infiltrating neuroglial tumor, typically located in the cerebral hemispheres. "SCG3 was first identified by our preliminary proteomic study as a protein with 2.1-fold higher expression in oligodendrogliomas than GBMs." (PMID 34257545, 2021).
small cell lung carcinoma (1 paper, 2017). Small cell lung cancer (SCLC) is a highly aggressive malignant neoplasm, accounting for 10-15% of lung cancer cases, characterized byrapid growth, and early metastasis. "SCG3 was identified as the most sensitive and specific marker for circulating tumor cells in small cell lung cancer and was indicative of a worse survival outcome." (PMID 29050227, 2017).
Tinnitus (1 paper, 2022). Tinnitus is an auditory perception that can be described as the experience of sound, in the ear or in the head, in the absence of external acoustic stimulation. "The present study showed that noisy workplaces decreased plasma concentrations of ST3GAL6 and SCG3, proteins thought to protect against tinnitus." (PMID 35602164, 2022).
tumor (9 papers, 2008 to 2026). "The three most highly overexpressed genes: SCG3 (26.6 fold), SCG2 (15.3 fold) and DDC (9.6 fold), have previously been shown to be linked to NE tumour biology, thus confirming the reliability of our study design." (PMID 18827820, 2008). "Given the complex regulation of gene expression, several key upregulated genes were found, including GATA4, SALL3, IL33, SOX10, and SCG3/SHC4, while the downregulation of keratin genes suggests a loss of epithelial differentiation, contributing to aggressive tumor behavior." (PMID 40647405, 2025). "To corroborate the assumption that the SCG3 expression detected in the blood of SCLC patients is derived exclusively from tumor cells, we optimized a noninvasive methodology using real-time quantitative PCR to detect SCG3 transcript traces in the peripheral blood of SCLC patients." (PMID 33809582, 2021). "As RE-1 silencing transcription factor is a transcriptional repressor in cancer, higher expression of SCG3 mRNA may increase the aggressive potential of the tumor or reduce the drug sensitivity of RE-1 silencing transcription factor depleted tumors." (PMID 29050227, 2017). "Moreover, the correlation of the SCG3 transcript with SCLC condition corroborates the idea that it could represent a specific marker of tumor cells population." (PMID 33809582, 2021). "The profiled tumor cells expressed most general PNEC markers (e.g. SCG5, CHGB, SCG2, PCSK1N, CHGA, SCG3) indicating retention of PNEC identity." (PMID 36469459, 2022). "However, TCF7L1, SCG3 and SV2C were the specifically expressed genes of tumor cell subtypes in primary tumor sites." (PMID 35494058, 2022). "Compared with tumor cells at the primary site, metastatic tumor cells still retained high expressions of KRT8 and KRT18, whereas metastatic tumor cells no longer expressed MMRN1, PROX1, TCF7L1, SCG3 and SV2C." (PMID 35494058, 2022). "The three most highly overexpressed genes in the NE vs the non-NE tumour cell group (SCG3, SCG2 and DDC), have all previously been described in the context of NE tumour biology, thus confirming the reliability of our study design." (PMID 18827820, 2008).
cancer (8 papers, 2012 to 2025). A tumor composed of atypical neoplastic, often pleomorphic cells that invade other tissues. "We find that somatic mutations create or disrupt putative miRNA target sites in the 3′UTRs of many genes, including several genes, such as MITF, EPHA3, TAL1, SCG3, and GSDMA, which have been previously associated with cancer." (PMID 23091610, 2012). "For example, increased expression of TAL1, SCG3 and GSDMA has been observed in cancers, and somatic mutations in the 3′UTRs of these genes disrupt putative targets of miRNAs that have been associated with cancer." (PMID 23091610, 2012).
CNS tumors (1 paper, 2021). "In a pilot study of plasma from 15 PCNSL, 5 other CNS tumors and 6 healthy individuals, methylation in cg0504 and SCG3 was detectable in 3/15 PCNSL samples (20%)." (PMID 33952317, 2021).
proliferative retinopathy (1 paper, 2023). "We recently reported that secretogranin III (Scg3) induces only pathological angiogenesis through VEGF-independent pathways, and Scg3-neutralizing antibodies selectively inhibit pathological but not physiological angiogenesis in mouse proliferative retinopathy models." (PMID 37509549, 2023).
SCG3 also shares sentences with these, for which no sentence is quoted: prostate carcinoma (2 papers); astrocytoma (1); breast carcinoma (1); cholesterol metabolism disorder (1); chronic lymphocytic leukaemia (1); colon cancer (1); endothelial dysfunction (1); lung adenocarcinoma (1); maturity-onset diabetes of the young (1); oligodendroglial tumor (1); rheumatoid arthritis (1); seminoma (1); Sleep apnea (1); testicular seminoma (1); type 2 diabetes (1).